GRN (granulin precursor)
Diseases named in the same sentence as GRN in open-access papers (continued):
Sharing a sentence is not in itself a finding about the gene and the disease.
Alzheimer disease (continued). "Interestingly, it has been previously demonstrated that GRN mutation carriers may show a phenotype resembling Alzheimer’s disease, with marked memory impairment associated with frontal lobe changes." (PMID 33216842, 2020). "Additionally, dysfunctional microglial phagocytosis is directly linked to FTD via mutations in GRN (progranulin) and may confer elevated risk of developing Alzheimer’s disease and ALS." (PMID 26578880, 2015). "GRN augmentation has been considered for the treatment of a series of neurodegenerative diseases including Parkinson's disease, Alzheimer's disease, and so on." (PMID 40736401, 2025). "For instance, the PILRA protein presents a pleiotropic effect on sick sinus syndrome and Alzheimer’s disease, whereas GRN exerts specific effects on the latter." (PMID 38820305, 2024). "Specifically, the PILRA protein presents a pleiotropic effect on both sick sinus syndrome and Alzheimer’s disease, whereas GRN exerts specific effects on the latter." (PMID 38820305, 2024). "In humans, heterozygous GRN mutations cause frontotemporal dementia (FTD) due to progranulin haploinsufficiency and reduced progranulin levels are a risk factor for Alzheimer’s disease." (PMID 37981208, 2023). "Missense mutations of GRN have been identified in diseases other than FTD, including ALS and Alzheimer’s Disease, although these are rare." (PMID 35095393, 2021). "PGRN has potential therapeutic activity in neurodegenerative diseases since it has been found that viral vector gene delivery of GRN suppresses the development of disease-like phenotypes in murine models of Parkinson’s disease (PD) and Alzheimer’s disease." (PMID 28358904, 2017). "Until now, more than 120 GRN mutations have been identified, excluding most missense variants of GRN that are risk factors for Alzheimer’s disease (AD) rather than FTD." (PMID 37628709, 2023). "Such parietofrontal asymmetry in neurodegeneration in the setting of positive family history and negative biomarkers for Alzheimer’s disease should raise the strong possibility of a GRN mutation." (PMID 33216830, 2020). "GRN is up-regulated in neurodegenerative diseases such as Alzheimer’s disease and multiple sclerosis and may function in neuro-inflammation." (PMID 31836762, 2019). "Homozygous GRN mutation carriers develop the lysosomal storage disorder NCL, and heterozygous carriers typically develop dominantly inherited FTD, though some develop other disorders such as Alzheimer’s disease, Parkinson’s disease (PD), or DLB." (PMID 31870439, 2019). "Increasing PGRN levels may be a viable therapeutic approach for GRN mutation carriers and more generally for FTD and Alzheimer's disease patients." (PMID 27356620, 2016). "It is well established that GRN gene mutations are associated with various kinds of neurological degenerative diseases, such as frontotemporal lobar dementia (FTLD), Parkinson’s disease, Alzheimer’s disease, multiple sclerosis, and amyotrophic lateral sclerosis." (PMID 26408020, 2015). "Protective relationships were similarly observed across proteinopathies, including FTD TDP-43 (C9orf72 and GRN), FTD tauopathy (MAPT), and Alzheimer’s disease, suggesting transdiagnostic relevance." (PMID 39816189, 2025). "GRN plays an important role in nervous system diseases, especially in neurodegenerative diseases such as Frontotemporal Lobar Degeneration (FTLD), Alzheimer's Disease (AD), Parkinson's Disease (PD) and Amyotrophic Lateral Sclerosis (ALS)." (PMID 40736401, 2025). "CSF levels of GRN, MMP‐10, and GPNMB were altered in Alzheimer's disease, preclinical Alzheimer's disease, and Parkinson's disease, respectively." (PMID 36504281, 2023). "The obvious parallels between GBA and GRN haplo-insufficiency raise immediate questions about the nature of pathogenesis in later onset neurodegenerative diseases such as FTD, Alzheimer's disease and Parkinson's disease." (PMID 26869920, 2016).
Alzheimer disease (continued). "Recently, the Ibero-American Alzheimer Disease Genetics Group Researchers analyzed the coding region and flanking sequences of APP, PSEN1, PSEN2, MAPT, and GRN by pooled-DNA exon sequencing in 167 clinical and five autopsy-confirmed, mainly EOAD cases." (PMID 25914626, 2015). "Mendelian randomization analyses suggested causal roles for several proteins, for example, ApoE, CD33, and GRN in Alzheimer's disease, MMP‐10 in preclinical Alzheimer's disease, SIGLEC9 in amyotrophic lateral sclerosis, and CD38, GPNMB, and ADAM15 in Parkinson's disease." (PMID 36504281, 2023). "For instance, the MAPT pathway is involved in the aetiopathogenesis of Alzheimer’s disease (AD), Parkinson’s disease (PD), parkinsonism, and amyotrophic lateral sclerosis (ALS); GRN in AD, PD, parkinsonism, motor neuron disease (MND); and C9orf72 in ALS, AD, and parkinsonism." (PMID 31405128, 2019).
Parkinson disease (70 papers, 2010 to 2026). A progressive degenerative disorder of the central nervous system characterized by loss of dopamine producing neurons in the substantia nigra and the presence of Lewy bodies in the substantia nigra and locus coeruleus. "The most common motor symptom in carriers of GRN pathogenic variants is parkinsonism, which is characterized by rest and postural tremors and rigidity." (PMID 40234992, 2025). "Recently, mutations in GRN have also been associated with the development of amyotrophic lateral sclerosis, Parkinson’s disease, and Alzheimer’s disease." (PMID 38643236, 2024). "ALS is extremely rare in those with GRN or MAPT mutations but a substantial minority can present with parkinsonism." (PMID 36385202, 2023). "Specifically, in GRN mutation carriers, the parkinsonism correlates with the degeneration and neural inclusions in the substantia nigra." (PMID 34458729, 2021). "A whole genome-wide sequencing study discovered evidence of enrichment of rare deleterious variants in the GRN gene amongst Parkinson’s disease cases relative to European controls." (PMID 33417599, 2021). "Recently, homozygous GRN mutations were reported to be associated with behavioral variant frontal dementia and Parkinsonism." (PMID 33886609, 2021). "The striatum is typically affected in GRN mutation carriers, consistent with the high prevalence of Parkinsonism in these patients." (PMID 34366786, 2021). "In a few cases, parkinsonism was described as the first or predominant clinical manifestation of a GRN mutation." (PMID 29370838, 2018). "Parkinsonism occurs quite frequently in patients with GRN mutation, but usually later in the disease course, after development of FTD." (PMID 29370838, 2018). "In a cohort of 32 French GRN mutation carriers, 13 (41%) developed parkinsonism during their disease course, but it was present at onset in only 1 patient." (PMID 29370838, 2018). "Herein, we investigated the effect of GRN rs5848 on the risk of Parkinson’s disease (PD) by genotyping 573 Taiwanese patients with PD and 490 age-matched control subjects." (PMID 23342160, 2013). "In conclusion, our findings confirm the phenotypic variability in GRN mutation carriers, which can also manifest with PD symptoms at an early age, further emphasizing the importance of performing a thorough genetic analysis in patients with parkinsonism." (PMID 40183420, 2025). "Mutations in the GRN gene can manifest as Parkinsonism, which clinically resembles IPD." (PMID 41302488, 2025). "Additionally, it has been previously reported that rs5848 significantly affects GRN mRNA levels both centrally and peripherally and has been linked to both AD and Parkinson’s disease." (PMID 38539243, 2024). "Individuals with GRN mutations and Parkinsonism could show reduced DOPA metabolism in bilateral corpus striatum by 18F-DOPA PET or reduced tracer uptake in left putamen by 123I-ioflupane SPECT." (PMID 36051222, 2022). "Mild Parkinsonism is a common clinical finding in GRN mutation carriers." (PMID 34366786, 2021). "Also, parkinsonism is common in GRN mutation carriers with FTLD and occurs more frequently than in other forms of FTLD." (PMID 31291241, 2019). "As with GRN mutations, patients may subsequently present parkinsonism, which rarely is the exclusive clinical presentation, and more often develops in association with bvFTD." (PMID 26388768, 2015). "There are indications that GRN mutations may play a role in other neurodegenerative diseases, such as amyotrophic lateral sclerosis, Parkinson’s disease, and AD, with increased PGRN levels having been shown to inhibit plaque formation and protect against amyloid beta toxicity in mouse models of AD." (PMID 39185427, 2024).
Parkinson disease (continued). "Interestingly, six cases exhibited ubiquitin/TDP43 immunopositive inclusions, all but two had tau pathology, and two of them exhibited α-syn inclusions, suggesting that this specific GRN mutation does not only contribute to the development of FTD but also to parkinsonism and α-syn pathology." (PMID 38037070, 2023). "Compared to MAPT, GRN mutations are characterized by higher phenotypic variability, including FTD, amyotrophic lateral sclerosis (ALS), typical Parkinson’s disease (PD), and dementia with Lewy bodies (DLB)." (PMID 40722695, 2025). "In contrast, GRN and MAPT mutation carriers had fewer individuals with symptoms, although in those who did have motor impairment, features were suggestive of parkinsonism (with fewer bulbar symptoms)." (PMID 36385202, 2023). "Other GRN polymorphisms associated with reduced PGRN levels also modify the risk for Alzheimer’s (AD) and parkinsonism." (PMID 36618392, 2022). "Parkinsonism with rigidity and akinesia is commonly seen in bvFTD,82 in sporadic FTD and especially in FTD arising from mutations in MAPT, GRN and C9orf72." (PMID 34458729, 2021). "An FTD case harboring the GRN p.Thr382fs mutation showed a phenotype resembling DLB, with fluctuations in cognition, parkinsonism and visual hallucinations." (PMID 31996268, 2020). "Further to this, the role of heterozygous GRN mutation in late onset neurodegenerative disorders appears similar to the relationship between GBA, another lysosomal gene, and Parkinson's disease." (PMID 26869920, 2016). "In brains of FTLD patients several CpG units in the GRN promoter are significantly hypermethylated compared to age-matched healthy controls, Alzheimer and Parkinson patients." (PMID 24252647, 2013). "GAA did not exhibit neurological signs of parkinsonism (described in around a third of GRN mutation cases) or motor neurone disease (a rare feature)." (PMID 19766663, 2010). "Though C9orf72, GRN and MAPT mutations most often result in bvFTD, they occasionally result in other neurodegenerative syndromes including primary progressive aphasia, amyotrophic lateral sclerosis, corticobasal syndrome, progressive supranuclear palsy, and parkinsonism." (PMID 39568670, 2024). "Parkinsonism is not uncommon in GRN mutation carriers and sporadic patients with FTLD." (PMID 36051222, 2022). "Parkinsonism is found in approximately 20–30% of patients in FTLD; in particular, it is frequently observed in familial FTD, with mutations linked to microtubule associated protein Tau (MAPT), progranulin (GRN or PGRN), and chromosome 9 open reading frame 72 (C9ORF72) repeat expansion." (PMID 33800495, 2021). "Compared to controls as well as patients with Alzheimer’s and Parkinson’s disease, sporadic FTLD brains exhibited altered expression of the DNA methyltransferase 3a as well as hypermethylation of the GRN gene promoter." (PMID 34366786, 2021). "Although parkinsonism occurs quite frequently in patients with FTLD with a GRN mutation, GRN genetic variability is unlikely to contribute significantly to susceptibility to PD." (PMID 29370838, 2018). "Nonetheless, in patients with an autosomal dominant history of atypical parkinsonism, TBK1 should be part of any atypical parkinsonism gene panel along with MAPT and GRN, and mutations in TBK1 suspected if other family members have ALS (which would not be seen in MAPT or GRN mutations)." (PMID 32980182, 2021).
lysosomal storage disorder (54 papers, 2014 to 2026). "Six years later, they were identified to be also linked to neuronal ceroid lipofuscinosis 11 (CLN11), a rare lysosomal storage disorder, expanding the spectrum of GRN-related neurodegenerative disorders." (PMID 40234992, 2025). "Rare homozygous loss-of-function mutations in GRN cause neuronal ceroid lipofuscinosis, a lysosomal storage disease with onset in young adulthood leading to premature death." (PMID 40596721, 2025). "On the other hand, Grn−/− mice “genetically correspond” to lysosomal storage disorders, such as CLN11 caused by homozygous GRN mutations." (PMID 40234992, 2025). "In contrast, homozygous loss of function mutations in GRN causes the severe lysosomal storage disorder neuronal ceroid lipofuscinosis." (PMID 38643236, 2024). "While heterozygous GRN mutations are a frequent cause of familial FTLD8,9, rare homozygous GRN mutations cause the lysosomal storage disorder neuronal ceroid lipofuscinosis." (PMID 38365772, 2024). "The presence of loss-of-function mutations on both GRN alleles, resulting in complete progranulin deficiency, causes the lysosomal storage disorder Neuronal Ceroid Lipofuscinosis (NCL), showing that progranulin is necessary for maintaining lysosomal function." (PMID 37118844, 2023). "Homozygous GRN mutations typically lead to the childhood to adolescent lysosomal storage disease “Neuronal ceroid lipofuscinosis type 11” (CLN11)." (PMID 36707901, 2023). "The dosage effect seen in the GRN gene has been replicated in many other lysosomal genes, in which homozygous mutations lead to early‐onset lysosomal storage disorders while heterozygous mutations lead to adult‐onset neurodegenerative diseases." (PMID 32852886, 2020). "Homozygous GRN mutations can cause a rare lysosomal storage disease, suggesting a plausible interaction between PGRN and tau in contributing to FTDs." (PMID 33177989, 2020). "In contrast to the late-onset neurodegenerative disease associated with heterozygous GRN mutations, homozygous loss-of-function GRN mutations result in neuronal ceroid lipfuscinosis, a pediatric lysosomal storage disease appearing with seizures, developmental delay, and vision loss." (PMID 36919702, 2023). "Similarly, it is interesting to note that null mutations in GRN can cause a lysosomal storage disorder and alterations in lysosomal homeostasis." (PMID 31405128, 2019). "Indeed, recent experimental work 33 indicates that mice homozygous for GRN mutation not only show evidence of a lysosomal disorder, similar to that seen in NCL, with elevated marker proteins, but also demonstrate TDP‐43 proteinopathy." (PMID 29790198, 2019). "Interestingly, a lysosomal storage disorder phenotype has also been reported in patients and mouse models with GRN mutations, suggesting some mechanistic overlap between GRN and CHMP2B." (PMID 28093491, 2017). "Lysosomal storage disease genes include GRN, GPNMB, GAA, and CHIT1 which, according to STRING analyses, interact with CD68, CD63, and TLR3, and are known to have lysosomal membrane function." (PMID 37422510, 2023). "The discovery that GRN-null individuals develop a lysosomal storage disease has encouraged investigations into the role of progranulin (PGRN) and granulin peptides in regulating lysosomal function." (PMID 33795008, 2021). "Homozygous GRN mutations cause neuronal ceroid lipofuscinosis-11 (CLN11), a lysosome storage disease." (PMID 33028409, 2020). "Recently, a potential role of PGRN in lysosome homeostasis has emerged based on the discovery that multiple cases of homozygous GRN mutation carriers develop neuronal ceroid lipofuscinosis-11 (CNL11), a lysosomal storage disease." (PMID 33028409, 2020). "FTD-GRN brains and iPSC-derived neurons with GRN mutations demonstrate impaired processing of PSAP to saposin C (a critical activator of GCase), resulting in reduced GCase activity, providing insight into the link with lysosomal storage disorders." (PMID 40234992, 2025).
lysosomal storage disorder (continued). "A41 was able to correct these lysosomal storage disease-related proteins back to GRN+/+ levels." (PMID 39033178, 2024). "Finally, in addition to GRN, we found upregulation of other lysosomal genes frequently dysregulated in lysosomal storage disorders such as NEU1, NPC2, PSAP, CTSD, LAMP1, and HEXA." (PMID 38643236, 2024). "The protective effects of TFEB in GRN KO cells and Grn–/– mice are consistent with many studies showing beneficial effects of TFEB overexpression in models of lysosomal storage disorders and neurodegenerative diseases." (PMID 40683940, 2025). "In a recent post-mortem analysis of a human brain carrying a homozygous GRN mutation, only a very mild TDP-43 pathology was described, without any positive detection of aggregated forms, while lysosomal storage disorder was overwhelming." (PMID 36430231, 2022). "Of note, some of the lysosomal enzymes with elevated levels in MUT brain (GRN, HEXA, and GLB1 – M36) are also implicated in lysosomal storage disorders, where they generally have decreased, rather than increased, function or expression." (PMID 33749590, 2021).
amyotrophic lateral sclerosis (41 papers, 2010 to 2025). Amyotrophic lateral sclerosis (ALS) is a neurodegenerative disease characterized by progressive muscular paralysis reflecting degeneration of motor neurons in the primary motor cortex, corticospinal tracts, brainstem and spinal cord. "Microglia are also a central element in the pathogenesis of other diseases including frontotemporal lobal degeneration and amyotrophic lateral sclerosis, as they are highest expressors of progranulin (GRN) and C9orf72 in the brain." (PMID 38654375, 2024). "TDP-43 is a major neuropathological protein accumulating in familial FTD (linked to mutations in GRN and C9orf72 genes) as well as in amyotrophic lateral sclerosis (ALS), and it normally contains various physiological functions such as RNA translation, autophagy, and synaptic plasticity." (PMID 33925655, 2021). "Familial forms of FTLD-tau are associated with mutations in the MAPT gene that encodes the tau protein, whilst mutations in Granulin (GRN), Valosin Containing Protein (VCP), or C9ORF72 genes can cause FTLD-TDP or amyotrophic lateral sclerosis." (PMID 23666556, 2013). "In amyotrophic lateral sclerosis (ALS), multiple ALS-related proteins, including TBK1, GRN, C9orf72 and TMEM106B, are implicated in endosomal sorting and endosomal lysosomal function." (PMID 38239560, 2023). "Finally, amyotrophic lateral sclerosis (ALS)-linked gene, including SOD1, and genes causing FTD, including GRN, are also robustly expressed in GNs at all assayed time points." (PMID 33281596, 2020).